FOXP3 (forkhead box P3)
Diseases named in the same sentence as FOXP3 in open-access papers (continued):
Sharing a sentence is not in itself a finding about the gene and the disease.
tumor (continued). "Although previous studies suggested that FOXP3 is an X-linked tumor suppressor gene in the breast and prostate gland, its biological function and importance in tumor cells have not been elucidated." (PMID 24649219, 2013). "Several previous studies reported that increased infiltration of FOXP3+ lymphocytes in the tumor microenvironment was associated with poor prognosis in cancer patients." (PMID 24649219, 2013). "Researchers have also confirmed that tumor-associated pDC strongly correlated with Tregs and that tumor-associated pDC altered functionality (loss of IFN-α secretion) was associated with Foxp3 +Tregs accumulation within BC." (PMID 24124553, 2013). "They showed that low numbers of tumour infiltrating FOXP3+ cells was associated with a good pathological response but did not characterise blood Tregs." (PMID 23320561, 2013). "A high infiltration by FOXP3+ lymphocytes was significantly associated with tumor grade III (P<0.001), HER2 positivity (P=0.03), ER negativity (P<0.001) and a triple-negative phenotype (ER−/PgR−/HER2−) (P=0.003)." (PMID 24649219, 2013). "The underlying mechanism(s) by which the expression of tumor FOXP3 affects prognosis require further investigation." (PMID 24649219, 2013). "Forkhead box protein P3 (FOXP3) expression in tumor infiltrating CD4+T cells is generally associated with an intrinsic capacity to suppress tumor immunity." (PMID 23977174, 2013). "A high density of tumor infiltrating Foxp3+ Treg in tumor specimen has been associated with poor outcome in various solid tumors, including ovarian, pancreatic, and hepatocellular carcinoma." (PMID 23382847, 2013). "In ductal cancers increased CD4+ and FOXP3+ TIL numbers are associated with more aggressive tumor features." (PMID 22471961, 2012). "In contrast, a complete clinical response has been suggested to be associated with disappearance of tumor infiltrating FOXP3+ T-cells during treatment." (PMID 22471961, 2012). "Her2/neu over-expression was significantly (p < 0.001) associated with increased numbers of tumor infiltrating FOXP3+ T cells and by a similar trend for CD4+ lymphocytes (p = 0.023)." (PMID 22471961, 2012). "Instead, the tumor infiltrating FoxP3+ T cells highly express memory/tumor-associated CCR8 and CXCR4." (PMID 22292042, 2012). "Almost all of the tumor-infiltrating FoxP3+ T cells express Helios, an antigen associated either with thymus-generated FoxP3+ T cells or activated T cells in the periphery." (PMID 22292042, 2012). "Impaired effector T-cell functions are often associated with increased numbers of CD4+CD25+FoxP3+ regulatory T cells in tumor-draining LN and tumor tissue." (PMID 22674057, 2012). "Low dose (5 mg/kg) entinostat reduced Foxp3 levels in Tregs and this was associated with enhanced tumor growth inhibition in combination with either IL-2 or a SurVaxM vaccine." (PMID 22303460, 2012). "Increased numbers of FOXP3-infiltrating tumor cell nests have been demonstrated in several neoplasms, and this event is generally associated with unfavourable clinical outcomes." (PMID 22162710, 2011). "In concordance with earlier reports that tumour infiltrating FOXP3+, CD8+ and CD45RO+ T cells are associated with better patient survival, our study confirms the importance of T cell density as a prognostic marker in CRC." (PMID 21818290, 2011). "This event is coordinated by many inflammatory cells, among them FoxP3+ Treg-cells are thought to suppress T cell immunity to tumor-associated antigens and to facilitate tumor progression." (PMID 21559338, 2011). "In a previous work, we have demonstrated that the CD8/Foxp3 ratio in tumour bed after chemotherapy is associated with a favourable outcome." (PMID 21750556, 2011). "The presence of FoxP3+ regulatory T cells, indicative of an immunosuppressive tumor microenvironment, was also variably associated with positive response." (PMID 22123319, 2011).
tumor (continued). "Further expansion occurring in the tumor is associated with induction of the Foxp3 expression and acquisition of the suppressor phenotype." (PMID 21049016, 2010). "The presence of Foxp3+ regulatory CD4+ T cells in tumor lesions is considered one of the major causes of ineffective immune response in cancer." (PMID 21049016, 2010). "Exposure of A/J mice to a tobacco carcinogen tripled lung-associated Foxp3+ cells prior to tumor development." (PMID 19330036, 2009). "The depletion of lung-associated Foxp3+ cells preceded tumor development because the number of Foxp3-expressing cells was decreased by 84% after 1 week of treatment (when tumors were not visible)." (PMID 19330036, 2009). "Regardless, it has been shown that accumulation of Tregs in tumor, as measured by Foxp3 expression, has been associated with a worse prognosis in patients with ovarian cancer." (PMID 19604349, 2009). "In conclusion, this study indicates that treatment of MPM with intra-pleural IL-2 leads, on one hand to an increase in tryptase-positive MCs, and in CD8+ and Foxp3+ lymphocytes, and on the other hand to an inhibition in tumour-associated vascularity." (PMID 19935800, 2009). "Interestingly, induced Foxp3 protein degradation preferentially destabilized intratumoral Treg cells, leading to a loss of suppressor function and tumor rejection." (PMID 40470210, 2025). "In addition, FOXP3+ Treg infiltration was associated with increased PD-L1 expression in multiple cancer types, suggesting a potential synergistic role in the tumor immune evasion." (PMID 40806346, 2025). "-High relevance: High PD-L1 and Foxp3 associated with immune escape and tumor progression." (PMID 40650089, 2025). "Furthermore, IHC staining and western blot analysis verified less PD-L1 expression and FOXP3 + Treg cells but more CD8 + cells in mice tumor tissue caused by PAQR5 knockdown (P < 0.01)." (PMID 40336138, 2025). "Finally, induced Foxp3 protein degradation preferentially destabilized intratumoral Treg cells, leading to a loss of function and tumor rejection." (PMID 41062655, 2025). "The authors concluded that an increased percentage of FoxP3+ Tregs in PTC tissues compared to FoxP3+ Tregs may be associated with tumor aggressiveness, suggesting that patients with HT concomitant with PTC may have better prognoses than those with simple PTC." (PMID 40313970, 2025). "Aberrant expression of FOXP3 in ovarian and other epithelial tumors has been implicated in the suppression of antitumor immune responses, thereby promoting tumor immune evasion and contributing to oncogenic pathway activation, including cross-talk with EGFR-mediated signaling cascades." (PMID 41301890, 2025). "High FOXP3 expression is typically associated with poor prognosis due to its role in immune suppression, which may facilitate tumor growth and resistance to therapies." (PMID 40735045, 2025). "This transient expression of Foxp3 could act as a feedback mechanism to quickly turn off the activation state of tumor-infiltrating effector T cells, contributing to the loss of antitumor responses." (PMID 39075226, 2025). "Our findings extend this knowledge by demonstrating that FGFR2 expression is positively correlated with markers of an immunosuppressive TIME, namely CD163+ macrophages and FOXP3+ regulatory T cells, and that these associations are particularly evident in luminal A tumours." (PMID 41018083, 2025). "However, evidence for pro-tumour development comes from the association of CD4+ Foxp3+ Tregs with poor clinical outcomes." (PMID 40351814, 2025). "In addition to cell division, it is possible that other, yet to be determined factors present in the tumor microenvironment contribute to the vulnerability of Treg transcriptional and functional features to the loss of Foxp3 in the tumor microenvironment." (PMID 40470210, 2025). "Tumor-associated Th17 cells with decreased glycolysis are reprogrammed to FoxP3+ Tregs." (PMID 39119332, 2024).
tumor (continued). "The expression of ANO1 in cancer cells, the expression of fibroblast activation protein (FAP) and alpha smooth muscle actin in cancer-associated fibroblasts (CAFs), and the numbers of CD8- and FOXP3-positive tumor-infiltrating lymphocytes (TILs) were evaluated using immunohistochemistry." (PMID 38352864, 2024). "As we have not found any data supporting a direct immunomodulatory effect of FoxP3 positive cells in CCH it remains to be clarified whether these cells are associated with tumor regression." (PMID 38962703, 2024). "In contrast, the majority of tetramer negative (Tetramer−) CD4+ T cells isolated from B16-3340 and B16-EV tumors, irrespective of SFB colonization, were regulatory-like T cells, expressing both T-bet and Foxp3, a phenotype associated with strong suppression of anti-tumor immune responses." (PMID 39185202, 2024). "Additionally, IL-2 signaling-mediated STAT5 activation is impaired in the TME with increased acidity, further inhibiting the antitumor function of CD8+ T cells while facilitating the reprogramming of tumor-associated Th17 cells to FoxP3+ Tregs." (PMID 39119332, 2024). "Additionally, intratumoral CD74KO Tregs show a decreased activation, a drop in Foxp3 expression, a low accumulation in the tumor, and consistently, they are associated with accelerated tumor rejection in preclinical models in female mice." (PMID 38702311, 2024). "Furthermore, tumours with higher infiltration levels of PD-L1+ lymphocytes in tumour islets were significantly associated with higher Foxp3+CD4+ T cell infiltration, despite the distribution of these cells." (PMID 39409156, 2024). "FOXP3 was closely associated with a variety of tumors, and involved in tumor immunotherapy." (PMID 39720726, 2024). "Similar to the published reports, the congenital deficiency of CD11chi DCs reduced the proportion of CD4+Foxp3+ Treg cells in lymphoid tissues under homeostatic and tumor-bearing conditions, suggesting the importance of CD11chi DCs in the maintenance of the population size of CD4+Foxp3+ Treg cells." (PMID 39206204, 2024). "Although its functional role may vary, numerous cancer studies have suggested that FOXP3 is highly expressed in tumor cells or T-cells, and that this high expression is associated with FOXP3 demethylation." (PMID 38331927, 2024). "Indeed, while the presence of FOXP3+ cells at the tumor center has been associated with better survival, the expression of FOXP3+ cells at the invasive margin is correlated with a worse prognosis." (PMID 38787209, 2024). "Particularly, the investigation of the mechanism regulating the expression of its key characteristic transcription factor Foxp3 in digestive malignancies offers a broad array of supportive therapeutic targets and early diagnostic markers with predictive value for tumor diagnosis and treatment." (PMID 38919615, 2024). "Additionally, tumor-associated pDCs can activate Foxp3+ Tregs through indoleamine 2,3-dioxygenase (IDO)." (PMID 38512518, 2024). "Finally, a high density of FoxP3− CD4+ helper T cells in the tumor margin was independently associated with favorable progression-free survival (PFS) and overall survival (OS)." (PMID 39683528, 2024). "Notably, the population of Foxp3 + Tregs showed no significant alteration, while a higher ratio of CD8 + T cells to Foxp3 + Tregs in the pre-treatment biopsies was associated with tumor regression." (PMID 38926205, 2024). "Moreover, stromal Foxp3 TILs was significantly associated with tumor response, history of prior radiotherapy, and grade 3/4 immune-related adverse events (irAEs)." (PMID 36662367, 2023). "This TREM2+ cluster was enriched for genes linked to pro-tumor pathways and could strongly interact with FOXP3+ Tregs through the IL1B/IL1R interaction, suppressing the anti-tumor effects." (PMID 38066642, 2023). "The N-terminal region of the protein was associated with the tumor-suppressor activity of Foxp3." (PMID 37766222, 2023).
tumor (continued). "Although Tregs are typically immunosuppressive and contribute to the immune escape of tumor, studies found that a high infiltration level of Foxp3+ Tregs was significantly associated with longer survival time of HNSCC patients, which were in accordance with our results." (PMID 36639648, 2023). "Variation in FOXP3, an intracellular key molecule for Treg development and function, has been associated with a dysregulation in subverting antitumor immune responses and promoting tumor progression." (PMID 37627102, 2023). "Similarly, in the murine lung tumorigenesis model, metformin treatment decreases tumor-associated FOXP3+ Treg cells due to activation of AMPK, which inhibits the mTOR pathway." (PMID 37686159, 2023). "The tumor-associated Th17 cells with low glycolysis capacity reprogram to FoxP3+Tregs." (PMID 37275901, 2023). "Quantitative multiplexed IF targeting the PD-L1 and PD-1 protein levels, CD68 + macrophages, CD8 + T cells, FOXP3 + regulatory T cells, and CK + tumor cells was used to assess the association between the complex tumor-immune interrelations and the risk of recurrence." (PMID 36959234, 2023). "Recently, many studies have found that Foxp3+ regulatory T (Treg) cells are the major immunosuppressive cells that facilitate the formation of TME by promoting the development of various tumor-associated cells and suppressing the activity of effector immune cells." (PMID 37936703, 2023). "Finally, other biological features, such as PIK3CA mutated status and differences in FOXP3+ populations in the tumor microenvironment, have also been proposed as potential explanations of the diverse prognostic impact of lymphocyte infiltration in luminal BC." (PMID 37345183, 2023). "However, this can be associated with enhanced levels of FoxP3 and other Treg effector molecules along with phenotypic similarities with the immunosuppressive tumor Tregs." (PMID 36992283, 2023). "Tumor CD274 overexpression has been inversely associated with FOXP3+ regulatory T‐cell (Treg) density in colorectal carcinoma, suggesting that tumor CD274 expression and Treg infiltrates might be mutually exclusive immunoevasion mechanisms." (PMID 37538192, 2023). "A meta-analysis examining the association of FOXP3+ cells with survival across different tumor types has shown varying directions of effect, and additional findings of a favorable association have been shown by IHC in ER-negative breast cancer and high-grade serous tubo-ovarian cancer." (PMID 36368129, 2023). "The increased Foxp3+ Tregs in the low-risk group may indicate persistently enhancing immune responses and thereby inhibit tumor progression." (PMID 36639648, 2023). "However, the associations and influences of FOXP3 polymorphisms to OSCC tumor progression and clinicopathological characteristics remained not well-investigated." (PMID 37215447, 2023). "On the other hand, mRNA expression of Ccl2 (macrophage chemotaxis marker), Cd68 (tumor associated macrophages, TAMs), Cd163 (M2 TAMs) and Foxp3 (regulatory T cells, Tregs) markers was greatly increased in LLC control mice, while this increment was less pronounced in 6-thio-dG-treated mice." (PMID 37085672, 2023). "The tumor-associated Th17 cells reprogram to FoxP3+Tregs in TME." (PMID 37275901, 2023). "However, the association between the preexisting CD8/FOXP3 ratio in the tumor microenvironment and the outcome of immunotherapy is still not clear." (PMID 35222387, 2022). "The underlying mechanisms that contribute to the increase of tumour-infiltrating FOXP3+ Treg cells could be categorised into three major pathways." (PMID 36569832, 2022). "Besides, a meta-analysis suggested that high Foxp3 (+) Tregs infiltration was significantly associated with shorter OS and more advanced tumor stage in ccRCC." (PMID 35689211, 2022). "Elevated FOXP3+ Tregs have been linked to poor OS and tumor metastasis in GC." (PMID 36405735, 2022).
tumor (continued). "report that mesenchymal high-grade serous ovarian cancer which is associated with poor survival showed high stromal density of fibroblasts and an enrichment for the CAF-S1 subtype, which was associated with a significant increase in FOXP3+ cells compared to tumours enriched with CAF-S4 fibroblasts." (PMID 35479076, 2022). "Moreover, high infiltration of FOXP3 + TILs and the presence of PD-L1 + immune cells were associated with tumor recurrence in DCIS patients." (PMID 35260954, 2022). "Furthermore, PDPN-positive CAFs express high TGF-β and PDPN-positive CAF cases display high CD204 TAMs and low CD8/FOXP3 T cells, which are associated with an immunosuppressive tumor microenvironment." (PMID 35159384, 2022). "Studies have shown that adequate density of mature DC in the tumor can prolong the survival of GC patients, and higher CD1/CD2 ratio and lower DC2 cell level are negatively correlated with the degree of tumor differentiation, degree of Foxp3+ Treg cells invasion and the risk of lymphatic metastasis." (PMID 35402261, 2022). "These associations suggest that CD4 and FoxP3 biomarkers may be used as a measure of a pro‐tumor immune infiltrate." (PMID 34626165, 2022). "Tumours high in FAP+CAFs are positively associated with an increase in FoxP3+ Treg infiltration." (PMID 35479076, 2022). "A large part of the immune suppression is mediated through tumor-associated regulatory immune cells such as tumor-associated macrophages (TAMs), tumor-associated neutrophils (TANs), FoxP3 + regulatory T cells (Tregs), and myeloid-derived suppressor cells (MDSCs)." (PMID 36066630, 2022). "Notably, VAT-Tregs from tumor bearing mice (both obese and lean) overexpressed Foxp3, correlating with the enhanced suppressive function of tumor-associated Tregs." (PMID 35472214, 2022). "Altogether, these data associate the role of FOXP3 in promoting tumor migration." (PMID 35562400, 2022). "In addition, high combined mean densities of CD8+, FOXP3+, and PD‐1+ TAICs in the tumor epithelium and stroma of biopsies were associated with a better response (TRG 1–3 versus 4, 5, p = 0.025 and p = 0.044, respectively)." (PMID 34743329, 2022). "Importantly, FOXP3 is regarded as tumour initiation in CC cells, and variants in the FOXP3 gene have been shown to be associated with HPV infection and precancerous lesions." (PMID 35322929, 2022). "The addition of OX40/TLR3/9 immunotherapy to SBRT resulted in local depletion of Tregs and tumor macrophages and reduced Treg-associated gene expression (FoxP3), suppressed macrophage-associated gene expression (IL-8), and suppressed exhausted T cell-associated gene expression (CTLA4)." (PMID 35055015, 2022). "Only GrB+ lymphocytes associated with FoxP3+ Tregs and tumor nest CD163+ macrophages." (PMID 36551965, 2022). "We have aimed to study the five-year disease-specific survival (DSS) of newly diagnosed OPSCC patients dependent on the activation level of TILs measured by level of CD3 and Foxp3-positive TILs, as well as the level of tumor-associated macrophages (TAM) measured by CD68-positive cells." (PMID 35326661, 2022). "Therefore, a deep understanding of underlying mechanisms of FOXP3+ Treg cells mediated immune homeostasis and anti-tumour immunity is required for developing more effective anti-tumour immunotherapies." (PMID 36569832, 2022). "A study of the molecular mechanism showed that FOXP3 promotes tumor metastasis and invasion might be associated with the upregulation of MMP2 and MMP9 expression." (PMID 36235242, 2022). "The induction of FOXP3 expression could be attributed to a specific property of tumor-associated macrophages (TAMs) in RCC." (PMID 36132332, 2022). "This may be relevant also in light of the observations herein, where down-regulation of CD163+ TAMs in Ndst1f/f CD11cCre+ mutants was also associated with a tumor phenotype showing reduction in FOXP3+ cells associated with tumors in mutant mice." (PMID 34715561, 2021).